Y_RNA (Y RNA )
Gene: Miscellaneous RNA gene on chromosome 20 (16,670,641 to 16,670,742, reverse strand). Ensembl gene ENSG00000200494.
Homologues: Orthologues: chimpanzee Y_RNA (97% identical), guinea pig Y_RNA (95% identical), macaque Y_RNA (90% identical). Paralogues in human: RNY3 (95% identical), Y_RNA (94% identical), Y_RNA (93% identical), RNY3P1 (92% identical), Y_RNA (92% identical), Y_RNA (91% identical), Y_RNA (90% identical), RNY3P14 (89% identical), Y_RNA (89% identical), Y_RNA (88% identical), RNY3P11 (87% identical), Y_RNA (87% identical), and 98 more.